NHLH2 (nescient helix-loop-helix 2)
Description:
Transcription factor which binds the E box motif 5'-CA[TC][AG]TG-3'. Involved in regulating energy expenditure, body mass, voluntary physical activity, mating behavior and reproductive longevity, acting through the hypothalamic-pituitary-gonadal axis. Acts as a transcriptional activator of target genes, including NDN, PCSK1, MC4R (By similarity). Is also a transcriptional activator of KISS1. May act centrally to regulate function of both white and brown adipose tissue. Together with NHLH1, required to maintain migration and survival of cells in the anterior extramural migration stream (aes), which forms the precerebellar nuclei. Also, in concert with NHLH1, may determine fate of gonadotropin releasing hormone-1 (GnRH-1) neurons.
Synonyms: bHLHa34; HEN2; NSCL2; HH27
Tractability: No criterion of Open Targets' tractability assessment is met for any kind of drug.
Gene: Protein-coding gene on chromosome 1 (115,836,377 to 115,843,917, reverse strand). Ensembl gene ENSG00000177551.
Subcellular location: Nucleus
Subcellular location (Human Protein Atlas): Nuclear bodies; Nucleoplasm
Gene Ontology:
Molecular function: protein binding; sequence-specific double-stranded DNA binding; transcription coactivator binding; DNA-binding transcription factor activity, RNA polymerase II-specific; RNA polymerase II cis-regulatory region sequence-specific DNA binding; DNA-binding transcription activator activity, RNA polymerase II-specific; protein dimerization activity; RNA polymerase II transcription regulatory region sequence-specific DNA binding; RNA polymerase II-specific DNA-binding transcription factor binding
Biological process: central nervous system development; positive regulation of transcription by RNA polymerase II; regulation of transcription by RNA polymerase II
Cellular component: chromatin; nucleus; transcription regulator complex
Genetic constraint (gnomAD): Loss-of-function variants: 7 observed, 6.74 expected, observed/expected ratio (o/e) 1.04, 90% interval 0.58 to 1.78. That is too few expected variants to judge how well the gene tolerates losing a copy. Missense variants: 155 observed, 178.54 expected, observed/expected ratio (o/e) 0.87, 90% interval 0.76 to 0.99. Synonymous variants: 93 observed, 89.14 expected, observed/expected ratio (o/e) 1.04, 90% interval 0.88 to 1.24.
Homologues: Orthologues: chimpanzee NHLH2 (100% identical), macaque NHLH2 (100% identical), guinea pig NHLH2 (99% identical), mouse Nhlh2 (98% identical), pig NHLH2 (97% identical), rat Nhlh2 (97% identical). Paralogues in human: NHLH1 (65% identical), TAL1 (37% identical), LYL1 (33% identical), TAL2 (24% identical).
Diseases named in the same sentence as NHLH2 in open-access papers:
NHLH2 is named in the same sentence as 19 diseases in open-access papers, as found by Europe PMC text mining. Sharing a sentence is not in itself a finding about the gene and the disease. The quoted sentences say what the papers report.
Obesity (11 papers, 2009 to 2025). Accumulation of substantial excess body fat. "This caused a ~15-fold increase of Nescient Helix-Loop-Helix 2 (NHLH2), a transcription factor that, when knocked out in mice, caused adult-onset obesity and reduced physical activity." (PMID 40101781, 2025). "Regarding its metabolic role, Nhlh2-KO mice displayed phenotypes reflective of PWS including obesity, hypogonadotropic hypogonadism and overall impaired metabolism." (PMID 40101781, 2025). "In a review published nearly 10 years ago, the authors pose five outstanding questions on NHLH2, including “Do human SNPs in NHLH2 contribute to any human obesity, physical activity, or fertility phenotypes?”." (PMID 36834605, 2023). "Previous studies have also described metabolic impairments (obesity) in Nhlh2 KO mice due to the decrease in the number of POMC neurons." (PMID 34494548, 2021). "The removal of Nhlh2 from Kiss1 neurons did not induce any metabolic phenotype in Kiss1Cre:Nhlh2fl/fl mice under regular or HFD chow, which supports a role for Nhlh2 in POMC neurons in the obesity phenotype of whole-body KOs." (PMID 34494548, 2021). "For example, NHLH2 KO mice show physical inactivity in young age (5–8 weeks) and overeating and obesity after 12 weeks, which resembles human middle age obesity." (PMID 31194049, 2017). "This sort of pattern is reminiscent of the action of NHLH2 that has been shown to reduce physical activity in mice and thereby increase body weight that eventually leads to adult-onset obesity." (PMID 19772584, 2009). "Additional roles of NHLH2 in the obesity and fertility has also been uncovered." (PMID 33245713, 2020). "Mice with a targeted deletion of the basic helix-loop-helix transcription factor, Nescient Helix-Loop-Helix 2 (Nhlh2), display adult-onset obesity with significant increases in their fat depots, abnormal responses to cold exposure, and reduced spontaneous physical activity levels." (PMID 20808804, 2010). "Additionally, variants in the Nhlh2 gene have been linked with obesity in humans, which together suggest that the reduced NHLH2 activity due to lack of SNORD116 in PWS may contribute to the obesity-related metabolic phenotypes seen in patients." (PMID 40101781, 2025).
neuroblastoma (6 papers, 2011 to 2023). Neuroblastoma (NB) is the most common solid, extracranial childhood tumor. "Higher expression levels of NHLH2 were found to be higher in unfavourable neuroblastomas and was significantly associated with a poor prognosis." (PMID 33245713, 2020).
Anxiety (5 papers, 2014 to 2025). Intense feelings of nervousness, tension, or panic often arise in response to interpersonal stresses. "Typically, activation of the SIRT1/NHLH2/MAO-A pathway is associated with increased anxiety behavior." (PMID 39595020, 2024). "Glucocorticoid signaling in the brain increases MAO-A mRNA levels, with SIRT1/NHLH2/ MAO-A pathways driving anxiety-like behavior." (PMID 39275174, 2024). "Glucocorticoid signaling in different brain areas can increase MAO-A mRNA levels via the SIRT1/NHLH2/MAO-A pathway, promoting anxiety-like behavior." (PMID 39335576, 2024). "Specifically, NHLH2 is hypoacetylated in SIRT1 OX mice compared to wild-type, highlighting SIRT1’s role in anxiety." (PMID 39275174, 2024). "Additionally, RES impacts the SIRT1/NHLH2/MAO-A pathway, which is known to enhance anxiety-like behavior." (PMID 39335576, 2024). "One such mechanism could involve the SIRT1/NHLH2/MAO-A pathway, in which SIRT1-induced deacetylation of NHLH2 transcription factors leads to increased MAO-A expression and decreased 5-HT levels in neurons, potentially exacerbating anxiety-like behaviors." (PMID 40427023, 2025).
hypogonadotropic hypogonadism (2 papers, 2021 to 2023). Abnormal ovarian or testicular function due to insufficient hormonal stimulation from the hypothalamic-pituitary axis. "Polymorphisms in NHLH2 have been implicated in human hypogonadotropic hypogonadism with the associated phenotypes of low exercise and increased body weight." (PMID 36834605, 2023). "Male Nhlh2-mutant mice develop hypogonadotropic hypogonadism and are infertile, which shows that Nhlh2 expression is critical for neuroendocrine development and maturation of the hypothalamic pituitary axis." (PMID 33731013, 2021).
cryptorchidism (1 paper, 2021). The failure of one or both testes of a male fetus to descend from the abdomen into the scrotum during the late part of pregnancy. "Nhlh2 KO male mice are infertile, presenting small penises at weaning, cryptorchidism, and no signs of puberty." (PMID 34494548, 2021).
depression (1 paper, 2023). "Therefore, suppression of SIRT1 expression can protect neuronal plasticity and maintain the 5-HT homeostasis via the NHLH2/MAO-A pathway, thereby improving depression-like behaviors." (PMID 37239191, 2023).
hypogonadism (1 paper, 2025). A disorder characterized by decreased function of the gonads. "NHLH2 is also associated with kisspeptin and the NHLH2 knockouts exhibit hypogonadism." (PMID 40136445, 2025).
medulloblastoma (1 paper, 2014). A malignant, invasive embryonal neoplasm arising from the cerebellum. "With this in mind, we assessed key transiently activated neural transcription factors (MATH1, NHLH1), and other temporally activated genes (NEUROD1, NHLH2, NFIB, LPPR4, DPYSL3, NEUROD2) expressed throughout granule neuron differentiation, in the medulloblastoma subgroups." (PMID 25412507, 2014).
metastatic disease (1 paper, 2021). "In the present study, we analyzed DNA methylation of INA, NHLH2, and THBS4 in normal, tumor, and metastatic renal tissue samples and found tissue-specific hypermethylation associated with the metastatic disease state, adverse clinical parameters, and shorter PFS." (PMID 35008203, 2021). "Methylation of the INA, NHLH2, and THBS4 loci was also measured in a subset of 136–142 primary tumor tissues free of lymph node or distant metastasis and a total of 202 cancer metastatic tissues isolated from 100 renal cell cancer patients suffering from metachronous metastatic disease." (PMID 35008203, 2021).
renal carcinoma (1 paper, 2021). A carcinoma arising from the epithelium of the renal parenchyma or the renal pelvis. "Thus, metastasis in RCC is significantly associated with methylation alterations in INA, NHLH2, and THBS4 loci, providing independent information for the potential early detection of aggressive renal cancers as a rationale for stratifying patients to adjuvant therapies." (PMID 35008203, 2021).
tumor (3 papers, 2020 to 2023). "Methylated TCGA KIRC based candidate CpG loci in INA, NHLH2, and THBS4 that are possibly associated with RCC metastasis were evaluated by pyrosequencing in 154 paired normal adjacent and primary tumor tissues, as well as in 202 metastatic tissues." (PMID 35008203, 2021). "Survival analysis using available follow-up data for a subset of tumors demonstrated a possible significant association of higher tumor methylation and shortened time to disease progression in univariate log rank analyses for INA, NHLH2, and THBS4 methylation." (PMID 35008203, 2021). "The molecular function activities; MAP kinase activity, retinol binding and RNA polymerase II activating transcription factor binding, enriched by the upregulated genes MAPK15, STRA16 and NHLH2, respectively, are activities that promote tumor cell proliferation." (PMID 33245713, 2020). "To analyze whether the candidate genes have tumor-specific hypermethylation, we measured 120, 141, and 132 corresponding pairs of adN and tumor tissue specimens for methylation of INA, NHLH2, and THBS4." (PMID 35008203, 2021). "In contrast, NHLH2 and THBS4 could be analyzed independent from tumor histology." (PMID 35008203, 2021).
NHLH2 also shares sentences with these, for which no sentence is quoted: cancer (3 papers); Adult onset (2); Hydrocephalus (1); infection (1); Infertility (1); Onset (1); Prader-Willi syndrome (1); renal cell carcinoma (1).